FGF19 (fibroblast growth factor 19)
Diseases named in the same sentence as FGF19 in open-access papers (continued):
Sharing a sentence is not in itself a finding about the gene and the disease.
cancer (continued). "Using single‐cell RNA sequencing (scRNA‐Seq) and clinical samples, fibroblast growth factor‐19 (FGF19, rodent FGF15) is found to mediate a significant interaction between CRC cells and cancer‐associated fibroblasts (CAFs), activating the hepatic stellate cells (HSCs)‐to‐CAFs differentiation." (PMID 39716892, 2025). "For example, FGF19 is known to regulate tissue remodeling and immune homeostasis, which may contribute to its protective role in cancer pathogenesis." (PMID 40817807, 2025). "FGFR4 binds to FGF19, an important factor in the development and progression of several cancers." (PMID 38540215, 2024). "FGF19 inactivation may be an effective therapeutic strategy for cancers and other malignancies involving the interaction between FGF19 and FGFR4." (PMID 37108717, 2023). "Studies have demonstrated that FGF19 is frequently amplified in human cancers." (PMID 36751636, 2023). "HCC harboring FGF19 amplification may represent a subset of cancers that are strongly addicted to the FGFR pathway." (PMID 37056769, 2023). "FGF19, one of the hormone-like FGFs, is frequently overexpressed and amplified in many cancers." (PMID 36751636, 2023). "As one of the important growth factors, FGF19 also regulates some other cancer-related pathways." (PMID 35463335, 2022). "These suggest that melatonin may have synergistic anti-cancer functions with FGF19 and FGFR4 inhibitors." (PMID 34576070, 2021). "The FGF19 genomic locus is on the chromosome 11q13.3, and is frequently amplified in human cancers." (PMID 32154250, 2020). "Thereby, the FGF19/FGFR4 axis is a potential therapeutic target in cancers." (PMID 32111983, 2020). "FGFR4 consistently activated by amplified FGF19 has been identified in several types of cancer." (PMID 30634399, 2019). "The FGF19 gene is located on chromosome 11q13.3, a region commonly amplified in human cancer." (PMID 30634399, 2019). "No such effect was observed in the FGFR4−/FGF19+ MDA-MB-231 cells or in the FGFR−/FGF19− MCF-10A cells, suggesting that only cancer cells that co-expressed FGFR4 and FGF19 might be susceptible to FGFR4/FGF19 inhibition." (PMID 27192118, 2016). "Therefore, FXR agonists and antagonists, as well as modulation of the gut microbiota, may offer novel strategies for treating FGF19-related cancers." (PMID 41328353, 2026). "However, there are limited experiments and studies related to FGF19 and cancer." (PMID 40072746, 2025). "The FGF19/FGFR4 pathway could be an alternative target for cancer prevention and management." (PMID 34576070, 2021). "However, the exact mechanism by which FGF19 influences the development of cancer remains unknown and requires additional studies." (PMID 34572066, 2021). "FGF19, functioning as an endocrine factor, is important in regulating metabolism under normal conditions, yet it could be critical for the progression of several cancers." (PMID 32111983, 2020). "In the field of cancer research and treatment, CRISPR-Cas9 provides new avenues for targeted therapies, exemplified by studies on the FGF19/FGFR4 signaling axis." (PMID 41328353, 2026). "Given the synergistic effects of FGF19 with MYC and KRAS, a therapeutic strategy targeting FGF19, MYC, and KRAS jointly is expected to become a new direction in cancer treatment." (PMID 41328353, 2026). "Due to the overexpression of S100A16 in PDAC and its role in promoting cancer progression through FGF19-mediated signaling pathways, S100A16, as well as the potentially involved FGF19 signaling pathways, are considered promising therapeutic targets for PDAC." (PMID 41328353, 2026). "These structural characteristics of FGF19 are essential in defining its role within the FGF family, while providing insights into potential therapeutic applications in cancer diseases." (PMID 41328353, 2026). "Fibroblast growth factor 19 (FGF19) and its receptor, FGFR4, present a significant axis in cancer biology, particularly in HCC." (PMID 41503573, 2026).
cancer (continued). "Their research indicated that some epigenetic drivers, like regulatory regions of ABCC1 and VEGFA, appeared in pan-cancer, while some epigenetic regulators, like FGF19, ASAP2 and EN1, and the PBX3 motif, are cancer specific." (PMID 40041484, 2025). "Among these genes, we identified FGF19, downregulated in all three datasets, which is known to promote epithelial-mesenchymal transition (EMT) and self-renewal capacity of cancer stem cells, and to induce cell cycle arrest in differentiated chondrocytes." (PMID 39568509, 2024). "Fibroblast growth Factor 19 (FGF19) plays a role in various physiological or pathological processes, including cancer." (PMID 37782406, 2024). "Moreover, over-expressed FGF19 could accelerate cancer progression and therapeutic resistance." (PMID 36751636, 2023). "In a murine model of lung orthotopic cancer, knockdown of CCND1 was found to prolong survival by attenuating FGF19-induced cell proliferation." (PMID 35463335, 2022). "All of FGF19, FGFR4, and KLB expression levels are greater in cancer tissues than in normal tissues next to malignancy." (PMID 36532586, 2022). "In contrast to the normal production and action of FGF19 as an endocrine hormone, FGF19 is overexpressed and co-expressed with FGFR4 in various cancers of liver, breast, lung, bladder, head, and neck, indicating FGF19 as a driver oncogene." (PMID 35296193, 2022). "FGF3, FGF4, and FGF19 are located at the 11q13.3 amplicon, which is one of the most frequent amplification sites in HCC and other cancers." (PMID 33802841, 2021). "Thus, targeting FGF19/FGFR4 could be a promising approach to combat cancers." (PMID 34576070, 2021). "These target genes include cancer stemness genes (e.g., sex-determining region Y-box 9 (SOX9), fibroblast growth factor 19 (FGF19), and SOX2), cytokines, and their receptor genes (e.g., interleukin-8 (IL-8) and IL-1 receptor, type II (IL-1R2))." (PMID 32859041, 2020). "Genomic profiling of ESCC tumors found 98% patients having amplification in one or more cancer‐relevant genes, as well as the co‐amplification of genes at adjacent chromosome locations, such as CCND1/FGF19 and TERC/SOX2/PIK3CA." (PMID 31851786, 2020). "The FGF19/FGFR4 signaling is known to promote invasion and metastasis in several different types of cancer." (PMID 33066597, 2020). "Downstream pathways of FGF19/FGFR4 signaling, such as PI3K-AKT and MEK-ERK, lead to enhanced cell proliferation and survival in cancer cells." (PMID 33066597, 2020). "The regulation of the FGF19/15 gene is considered a critical factor in understanding its role in cancer, particularly in non-hepatocyte-derived cancers." (PMID 41328353, 2026). "Despite these insights, a significant gap in the understanding of the regulation of the FGF19/15 gene in non-hepatocyte-derived cancers remains." (PMID 41328353, 2026). "The inhibition of FGF19, achieved through methods such as siRNA-mediated silencing or neutralization by an anti-FGF19 antibody, specifically decreases AKT phosphorylation, suppresses cancer cell growth, and enhances doxorubicin sensitivity in FGFR4+/FGF19+ BC cells." (PMID 41328353, 2026). "The oncogenic role of FGF19 in LUSC has been partially elucidated; therefore, a combined inhibition strategy targeting both FGF19 and CCND1 may offer a promising therapeutic pathway for the treatment of this cancer." (PMID 41328353, 2026). "It is likely that these genes could also be co-amplified and overexpressed with FGF19 in LUSC, and contribute to the cancer phenotype." (PMID 35463335, 2022). "FGF19 amplification-induced FGFR4 activation was observed in hepatocellular carcinomas and might represent FGFR4-dependent cancer subtype 1,2,8-10." (PMID 36168616, 2022). "Melatonin could inhibit cancer cell growth and downregulate matrix metallopeptidase 9 (MMP-9) and fibroblast growth factor 19 (FGF19) to inhibit cancer cells’ invasion and migration." (PMID 35409137, 2022).
cancer (continued). "As targeting FGFR4 becomes increasingly more feasible than directly targeting FGF19, highly selective FGFR4 inhibitors have become commercially available for preclinical tests, providing new approaches to treat a subgroup of FGF19-driven cancers." (PMID 33691750, 2021). "Since FGF19/FGFR4 signaling acts as an oncogenic pathway and is involved in the cancer progression, targeting FGF19/FGFR4 signaling might be an effective anticancer therapy." (PMID 34576070, 2021). "To date, the possible involvement of FGF19/FGFR4 signaling in cancer stem cells (CSCs) has not been definitively established." (PMID 33066597, 2020). "Analyses of transcripts altered in TMED3 kd cells over control levels revealed a group of 63 RNAs enhanced twofold or more that included several genes previously shown to promote pro-metastatic behavior in different cancers, including SOX8, ASCL2, FGF19, and CXCR4." (PMID 31253868, 2019). "The results from the analysis of serum and tissues encouraged us to further analyze the histological distributions of FGF19 and its receptor FGFR4 as well as EpCAM, a potential cancer stem cell marker, corresponding to the clinical histological stages, including ST, NASH, CR and HCC." (PMID 27447573, 2016). "The data from FGF19 expression with FGFR4 and EpCAM expression from the 24 immunohistochemically stained HCC sections were used to determine the correlation between FGF19 and its receptor FGFR4 and between the cancer stem cell marker EpCAM, respectively, in the ST-NASH-CR- HCC sequence." (PMID 27447573, 2016). "Furthermore, PXR can directly bind to the promoter region of the FGF19 gene via DR3 and ER6 elements in both cancer and normal intestinal crypt cells." (PMID 24690092, 2014). "However, the potential role of the gut microbiota, particularly bacterial species that metabolize bile acids to produce FXR agonists and antagonists, in influencing cancer through FXR signaling and FGF19/15 induction remains largely unexplored in many other tumors." (PMID 41328353, 2026). "It is possible to suggest that FGF19 may have dual roles depending on the presence or absence of cancer cells." (PMID 39716892, 2025). "Further investigations are needed to explore more details about the melatonin-FGF19/FGFR4 network, which may help us to obtain a better understanding on cancer progression and find more approaches to tackle malignant tumors, not only in the head and neck but also in other systems." (PMID 34576070, 2021). "On the other hand, directly targeting FGF19 in LSQ might not be very effective since FGF19 could be highly expressed during cancer progression." (PMID 32111983, 2020). "Even though FGF19, FGF21 and FGF23 are all endocrine factors, based on the effects of FGF21 on fuel energy, oxidative stress, life-span and its pleiotropic metabolic actions; investigators have suggested that FGF21 is a very promising molecule with therapeutic potential to combat cancer." (PMID 27358750, 2016). "In addition, studies based on mouse models indicate that individual overexpression of FGF19 and/or FGFR4 are not the only risk factors for HCC and other cancer types since FGFR4 hyperactivation mediated by abnormal FGF19 expression and, consequently, signaling is just an important issue." (PMID 34200439, 2021). "A positive correlation between hemoglobin and FGF19 in HCC patients 24 h post-transplant, which we do not observe in other diseases, may be due to the unique metabolic needs and the body’s specific response to liver regeneration in the context of prior cancer." (PMID 39941067, 2025).
metabolic disorders (39 papers, 2012 to 2026). "Fibroblast growth factor 19 (FGF19) has received increasing attention in metabolic disorders of the skeletal system, but its role in cartilage development is poorly understood." (PMID 40765829, 2025). "Previous reports have shown that circulating FGF19 levels are reduced in individuals with metabolic disorders and MASLD." (PMID 38587078, 2024). "The recognition of KLB as an exciting drug target for a variety of common metabolic diseases encouraged many pharmaceutical companies to develop a multitude of FGF19 and FGF21 analogs." (PMID 37260446, 2023). "Through analyzing the DMs between LPS vs. control group and LPS vs. FGF19 + LPS group, 25 DMs were screened and potentially involved in the protective roles of FGF19 in LPS-induced metabolic disorders." (PMID 35847588, 2022). "The plasma levels of FGF19 were significantly decreased in T2DM and obese patients, while injection of recombinant FGF19 protein significantly improved metabolic disorders in db/db mice and DIO mice." (PMID 36386219, 2022). "The findings lend support to the pro-tumorigenic potential of FGF15/FGF19 in the metabolic disorder microenvironment and address the importance of the role that FGF15/FGF19 play in HCC development." (PMID 33935756, 2021). "Since endocrine FGFs that include FGF19 act as circulating hormones related to several metabolic diseases, the impact of their serum concentration for metabolic diseases was investigated." (PMID 30720727, 2019). "Since the function of FGF19 and FGF21 is dependent on β-klotho as a co-receptor; decreased expression of β-klotho causes metabolic disorders." (PMID 31151464, 2019). "As the role of FGF19 is becoming more and more important in the pathogenesis of many metabolic diseases, we proposed that the thyroid hormone level should be taken into account when the serum concentration is explained." (PMID 27684859, 2016). "As the roles of FGF19 are more and more important in the pathogenesis of many metabolic diseases, we proposed that the thyroid hormone level should be taken into account when the serum concentration is explained." (PMID 27684859, 2016). "Pharmacological activation of the FGF19 pathway has attractive therapeutic potential for treatment with metabolic disease and bile acid-related hepatobiliary disorders, and in fact, FGF19 analogs are currently being tested in clinical trials." (PMID 26634251, 2015). "Manipulation of expression or pharmacological administration of FGF19 or FGF21 protein in mice has major impact on metabolic diseases and pathways in hepatocytes in addition to adipocytes." (PMID 23106963, 2012). "Pharmacological administration of FGF19 improves metabolic disorders such as T2D and NAFLD." (PMID 37260446, 2023). "FGF19 pretreatment alleviates LPS-induced metabolic disorder and organ injury." (PMID 35847588, 2022). "Human fibroblast growth factor 19 (FGF19) plays a therapeutic role in metabolic diseases." (PMID 33751819, 2021). "In contrast to FGF21 however, metabolic diseases exhibit reduced serum FGF19 levels." (PMID 33204460, 2020). "Interestingly, decreased levels of FGF19 have been reported in patients with NAFLD and other metabolic disorders, however, the underlying mechanisms are poorly defined." (PMID 30609782, 2019). "The putative protective effect of FGF19 in relation to CAD might involve its influence on metabolic disorders." (PMID 23940810, 2013). "Acupuncture treatment significantly reduced serum fibroblast growth factor 19 (FGF-19) levels, suggesting suppression of intestinal FXR signaling—a pathway implicated in hepatic metabolic regulation and recognized as a therapeutic target for metabolic disorders." (PMID 41514462, 2026). "FGF19 could also be a new therapeutic target for metabolic diseases." (PMID 36532504, 2022).
metabolic disorders (continued). "However, considering tissue specificity, following studies could further explain the mechanism of the connection between BAT and the MGBA mediated by FGF19 via the neuroendocrine aspect, and how to apply this connection to the treatment of metabolic diseases." (PMID 35280695, 2022). "Current clinical data already support bile acid-based strategies in metabolic disease and neuroprotection, while novel agents targeting FXR, TGR5, and FGF19 signaling are emerging as promising tools for restoring disrupted gut–brain communication." (PMID 41465592, 2025). "Meanwhile, pharmaceutical companies have designed and tested a multitude of FGF19- and FGF21-mimetics, recognizing KLB as a promising drug target for treating various metabolic diseases in humans." (PMID 37260446, 2023). "Through the development of FGF19- and FGF21 mimetics, KLB has emerged as a promising drug target for treating various metabolic diseases, such as type 2 diabetes (T2D), non-alcoholic fatty liver disease (NAFLD), and cardiovascular disease." (PMID 37260446, 2023). "Current studies on the endocrine FGF family have demonstrated the importance of FGF19, FGF21, and FGF23 in human genetic and metabolic disorders, suggesting their therapeutic role in metabolic diseases." (PMID 34572066, 2021). "The therapeutic potential of both FGF19 and FGF21 in the treatment of metabolic disorders has been discussed extensively in the literature." (PMID 22675463, 2012). "FGF-19 is another protein of the FGF family and plays an important physiological role in the regulation of glucose and lipid metabolism, thus offering promising approaches for therapeutic strategies in metabolic disorders." (PMID 37239098, 2023). "In addition, produced by ileal enterocytes, fibroblast growth factor 19 (FGF19) and its mouse orthologue FGF15, are favored in the treatment of metabolic diseases." (PMID 35280695, 2022). "Also, the possibility is raised that FGF19 may serve as a more comprehensive target in those patients whose metabolic disorder symptoms are not fully improved by thyroid hormone replacement alone." (PMID 27684859, 2016). "It was found that FGF15, unlike FGF19, could not induce HCC in the mouse models of metabolic diseases, even at supra-pharmacological exposure levels." (PMID 29973237, 2018).
cardiovascular disease (7 papers, 2018 to 2026). "Smoking is an important risk factor for cardiovascular disease and as FGF19 has also been shown to be associated with cardiovascular risk factors, we tested any association between FGF19 levels and smoking habits." (PMID 39341924, 2024). "Another possible explanation is that patients with cardiovascular disease have reduced hepatic responsiveness to FGF19, leading to a compensatory increase in serum FGF19 levels, which is consistent with an increased risk of cardiovascular disease." (PMID 32528406, 2020). "However, studies that have assessed the association between FGF-19 and cardiovascular disease are limited." (PMID 31443313, 2019). "Data from 1,018 participants with valid serum FGF19 measurements from the Shenzhen–Hong Kong United Network on Cardiovascular Disease study were analyzed." (PMID 41522208, 2026). "Although smoking is an important cause of cardiovascular disease, the association between FGF19 and smoking has not previously been described." (PMID 39341924, 2024).